ENSG00000251822
Gene: Small nucleolar RNA gene on chromosome 12 (60,363,822 to 60,363,935, forward strand). Ensembl gene ENSG00000251822.
Homologues: Paralogues in human: SNORA19 (65% identical).